SPIN2A (spindlin family member 2A)
Description:
May be involved in the regulation of cell cycle progression (By similarity). Exhibits H3K4me3-binding activity.
Synonyms: DXF34; SPIN2; TDRD25; dJ323P24.1
Tractability: PROTAC: ubiquitination databases record sites on it.
Chemical probes: VinSpinIn (high quality)
Gene: Protein-coding gene on chromosome X (57,134,530 to 57,137,679, reverse strand). Ensembl gene ENSG00000147059.
Subcellular location: Nucleus
Subcellular location (Human Protein Atlas): Nucleoplasm
Gene Ontology:
Molecular function: histone H3K4me3 reader activity; protein binding
Biological process: regulation of DNA-templated transcription; chromatin organization; gamete generation
Cellular component: nucleoplasm; nucleus
Homologues: Orthologues: tropical clawed frog spin1 (79% identical), zebrafish spina (72% identical), rat LOC134484257 (61% identical), rat LOC134486234 (61% identical), rat LOC134486240 (59% identical), rat LOC134486221 (57% identical), rat Ssty1-ps5 (54% identical), mouse Gm20737 (53% identical), mouse Gm20772 (53% identical), mouse Gm20773 (53% identical), mouse Gm20777 (53% identical), mouse Gm20807 (53% identical), and 50 more. Paralogues in human: SPIN2B (99% identical), SPIN1 (78% identical), SPIN3 (74% identical), SPIN4 (63% identical).
Diseases named in the same sentence as SPIN2A in open-access papers:
SPIN2A is named in the same sentence as 1 disease in open-access papers, as found by Europe PMC text mining. Sharing a sentence is not in itself a finding about the gene and the disease. The quoted sentences say what the papers report.
lung adenocarcinoma (1 paper, 2014). A carcinoma that arises from the lung and is characterized by the presence of malignant glandular epithelial cells. "Although the primer specificity of SPIN2A was not high enough so that additional bands appeared in addition to the strongest and expected band, SPIN2A has been detected by microarray in lung adenocarcinoma (Expression Atlas)." (PMID 24743329, 2014).